LGALS9 (galectin 9)
Diseases named in the same sentence as LGALS9 in open-access papers (continued):
Sharing a sentence is not in itself a finding about the gene and the disease.
Arthritis (21 papers, 2010 to 2025). Inflammation of a joint. "The use of recombinant galectin-9 in rats with adjuvant-induced arthritis inhibited inflammatory bone destruction, indicating that exogenous galectin-9 has therapeutic potential in patients with RA." (PMID 37884496, 2023). "In order to clarify the Tim-3/gal-9 complex, a large amount of galectin-9 was administered to rats with arthritis, and bone destruction was consequently observed." (PMID 31600237, 2019). "Taken together, galectin-9 is a negative regulator of arthritis as suggested by both animal and human studies." (PMID 24416634, 2013). "LGALS9 encodes galectin‐9, one of four ligands for the immune checkpoint receptor TIM‐3, also known as hepatitis A virus cellular receptor 2; blockade of TIM‐3 ameliorates arthritis in a mouse model." (PMID 39887658, 2025). "Other studies have found that galectin-9 is being used in patients with RA and may be beneficial in collagen-induced arthritis of mice when administered exogenously." (PMID 31600237, 2019). "As discussed in the section of galectin-9 in arthritis animal models, administration of human stable recombinant galectin-9 ameliorated arthritis in CIA and an immune complex-induced arthritis mouse model, assessed by pannus formation, inflammatory cell infiltration, and bone/cartilage destruction." (PMID 24416634, 2013). "Furthermore, knockout of LGALS9 ameliorated nephritis and arthritis in a murine model, which all suggested that galectin-9 may have a role in disease pathogenesis." (PMID 39050398, 2024). "Furthermore, galectin-9 was shown to negatively regulate macrophage activation by increasing the expression of immunoinhibitory FcRIIb and decreasing the expression of immunoactivating FcRIII, leading to the suppression of arthritis in an immune complex-induced arthritis mouse model." (PMID 24416634, 2013).
Sepsis (19 papers, 2013 to 2025). Sepsis is defined as life-threatening organ dysfunction caused by a dysregulated host response to infection. "By combining these two analytical methods, we found that the low expression of LGALS9 in sepsis patients is associated with the activation and differentiation of CD14+ monocytes and CD4+‐naive T cells." (PMID 39044269, 2024). "Together our findings indicate that galectin-9 plays a pathogenic role as an alarmin to exacerbate the inflammatory response during pulmonary infection with Francisella and contributes to sepsis development." (PMID 25898318, 2015). "Additionally, we found that the activation and differentiation of CD4+‐naive T cells are also linked to low expression of LGALS9 in sepsis patients." (PMID 39044269, 2024). "Our current study shows that galectin-9, a host lectin, plays a pathogenic role as an alarmin to exacerbate the inflammatory response during pulmonary infection with Francisella and contributes to sepsis development." (PMID 25898318, 2015). "Our analyses of galectin-9 expression, distribution, immune modulation and comparison of disease progression in F.n. infected galectin-9 sufficient and—deficient mice show that galectin-9 acts as an alarmin to exacerbate the inflammatory response in Francisella infection induced sepsis development." (PMID 25898318, 2015). "In subsequent analyses, combined with scRNA‐seq data, we further found that the decrease in LGALS9 expression level in sepsis patients has an impact on immune homeostasis." (PMID 39044269, 2024). "Subsequently, we performed scRNA‐seq analysis on a sepsis dataset, uncovering potential mechanisms that significantly suppress LGALS9 expression in sepsis." (PMID 39044269, 2024). "As reported in previous studies, LGALS9 (galectin‐9) exhibited a protective effect in polymicrobial sepsis, SIGLEC7 was an important negative regulator of acute inflammatory responses and was a potential target for the treatment of sepsis." (PMID 39044269, 2024). "Here we show that Galectin-9, a host endogenous β-galactoside binding lectin, functions as an alarmin capable of mediating inflammatory response during sepsis resulting from pulmonary infection with Francisella novicida, a Gram negative bacterial pathogen." (PMID 25898318, 2015). "In this study we have investigated the role of galectin-9, in the F.n. induced inflammatory response and sepsis." (PMID 25898318, 2015). "Collectively, these findings suggest that galectin-9 functions as a novel alarmin by augmenting the inflammatory response in sepsis development during pulmonary F. novicida infection." (PMID 25898318, 2015). "To further determine the effect of Tim-3 pathway on sepsis, we also examined the expression of galectin-9, a known ligand for Tim-3, and we observed that galectin-9 was indeed expressed on the surface of mouse peritoneal macrophages and neutrophiles." (PMID 25337993, 2014). "Galectin-9 exhibited a protective effect in polymicrobial sepsis as demonstrated in galetin-9 transgenic mice and therapeutic galectin-9 administration." (PMID 24321251, 2013). "In a polymicrobial sepsis model, galectin-9 improved animal survival." (PMID 41516283, 2025). "In this study, by integrating the results of SMR analysis and single‐cell RNA‐seq analysis, we have revealed that LGALS9 is expressed at lower levels in sepsis patients compared to healthy controls, and that low expression of LGALS9 promotes the activation and differentiation of CD14+ monocytes." (PMID 39044269, 2024). "Furthermore, based on single‐cell RNA sequencing data, we elucidated potential molecular mechanisms at single‐cell resolution and identified that LGALS9 inhibition in sepsis patients leads to the activation and differentiation of monocyte and T‐cell subtypes." (PMID 39044269, 2024). "Notably, compared to healthy controls, the expression of LGALS9 in sepsis patients was significantly reduced, particularly within the Mono_CD14 subtype." (PMID 39044269, 2024).
Sepsis (continued). "In this scenario a combinatorial approach using blockade of galectin-3 and galectin-9 along with antibiotics could potentially treat Francisella infection induced sepsis." (PMID 25898318, 2015). "This increase in galectin-9 expression at 3 dpi is consistent with the appearance of other sepsis features (extensive cell death, hyperinflammatory response, increased vascular injury) at this time, as reported in our previous studies with F.n. as well as the fully virulent F. tularensis." (PMID 25898318, 2015). "In summary, we speculate that the decreased expression of LGALS9 in sepsis patients may enhance the activation and differentiation of CD4+‐naive T cells, leading to their differentiation into regulatory T cells with stronger immune response capabilities during inflammation." (PMID 39044269, 2024). "Galectin-9 thus may represent a potential target for treatment of sepsis during this infection." (PMID 25898318, 2015). "In the Tn subtype, compared to the healthy controls, there was a decreasing trend in the expression of LGALS9 in sepsis patients, although it was not statistically significant." (PMID 39044269, 2024). "Moreover, in sepsis, the interactions of TIM-3 with its ligands, such as Galectin-9, HMGB1, or CEACAM1, may play a crucial role in modulating immune responses and influencing the outcome of sepsis." (PMID 38576606, 2024). "In addition, it has recently been reported that both LGALS9 and CD47 are co-inhibitory molecules, suggesting the LGALS9-CD47 pair might also contribute to the enhanced immunosuppressive effect of Tregs in elderly patients with sepsis." (PMID 38909272, 2024). "However, the effect of galectin-9 on polymicrobial sepsis has not been assessed." (PMID 24321251, 2013).
dengue (15 papers, 2010 to 2024). "In critical phase and recovery phase of dengue fever, the level of galectin-9 is significantly associated with IL-8, interferon-γ inducible protein 10, vascular endothelial growth factor (VEGF) and negatively correlated with monocyte percentage." (PMID 27240351, 2016). "Elevation plasma level of galectin-9 is detected after dengue virus infection and it is associated with disease severity." (PMID 27240351, 2016). "Previous reports have shown that dengue virus infection induced increased expression of galectin-9 at the cell-based protein or mRNA level." (PMID 28788062, 2017). "This study is a pilot examination of the effect of dengue virus infection on galectin-9 expression in monocytic THP-1 cells." (PMID 28788062, 2017). "Studies from another group of researchers demonstrated that serum galectin-9 levels are much higher in patients with dengue hemorrhagic fever than in patients with dengue fever only." (PMID 28991189, 2017). "In acute febrile phase, galectin-9 and galectin-3BP were induced in dengue patients compared to healthy controls." (PMID 27240351, 2016). "Our results showed the levels of galectin-9 and galectin-3BP were significantly higher in dengue patients than those in healthy controls." (PMID 27240351, 2016). "Interestingly, monocytes themselves produce galectin-9 in vitro and this increases in the presence of Dengue virus infection." (PMID 39822268, 2024). "We have studied full-length osteopontin (FL-OPN) and full-length galectin-9 (FL-Gal-9) in dengue patients and showed that the former directly correlated with D-dimer and ferritin levels, and the latter tracked viral load, and were associated with multiple cytokines and chemokines." (PMID 32610429, 2020). "Furthermore, our study indicated strong correlation between serum concentrations of galectin-9 and galectin-3BP in febrile dengue patients." (PMID 27240351, 2016). "The aim of this study was to investigate the serum concentration and potential interaction of soluble galectin-1, galectin-3, galectin-9, galectin-3 binding protein (galectin-3BP), glycoprotein 130 (gp130), and E-, L-, and P-selectin in patients with dengue fever in acute febrile phase." (PMID 27240351, 2016). "In addition, strong correlation between galectin-9 and galectin-3BP was observed in dengue patients." (PMID 27240351, 2016). "The level of galectin-9 and galectin-3BP in dengue patients was higher than in healthy controls." (PMID 27240351, 2016). "The level of galectin-9 in healthy controls was significantly lower than in other groups (10,287 pg/mL (7197–14,868) (dengue) vs. 9852 pg/mL (7806–13,932) (bacterial infection) vs. 10,515 pg/mL (7743–14,161) (OFI) vs. 5061 pg/mL (4691–6018) (healthy controls))." (PMID 27240351, 2016). "In summary, our study suggested galectin-9 and galectin-3BP might be critical inflammatory mediators in acute dengue virus infection." (PMID 27240351, 2016). "Since galectin-9 and galectin-3BP are reported to be induced from dengue virus infected-endothelial cells, we assume that both molecules regulate the interaction between monocytes and endothelial cells in acute febrile phase of dengue." (PMID 27240351, 2016). "Galectin 9, a Tim-3 ligand, is down-regulated in severe dengue patients." (PMID 20559541, 2010). "We have studied the roles of galectin-9 (Gal-9) and osteopontin (OPN) in dengue, HIV, and MTB infection." (PMID 33143141, 2020). "The results showed that the combined analysis of several markers, including eotaxin, galectin-9, IFN-α2, and monocyte chemoattractant protein-1, can help to detect 92% of dengue hemorrhagic fever and 79.3% of dengue fever patients." (PMID 28991189, 2017).
lymph node metastasis (15 papers, 2013 to 2025). "Galectin-9 was correlated with lymph node metastasis with 89% specificity and fair area under the curve (AUC) = 0.7 (p value (AUC = 0.5) = 0.005)." (PMID 36050693, 2022). "Low levels of galectin-9 expression were positively correlated with a poor histological grade and lymph node metastasis (P<0.05)." (PMID 27028892, 2016). "Expression of the ‘Vessel maturation’ marker LGALS9 was correlated with lymph node metastasis (p = 0.008)." (PMID 25889974, 2015). "In tumors, higher galectin-9 expression is associated with early TNM stage, no lymph node metastasis, good histological differentiation, and longer overall survival times." (PMID 27028892, 2016). "Significant differences were found in galectin-9 expression was according to TNM stage, lymph node metastasis, and histological grade but not gender, age, ordistant metastasis." (PMID 27028892, 2016).
pancreatic ductal adenocarcinoma (15 papers, 2020 to 2025). An infiltrating adenocarcinoma that arises from the epithelial cells of the pancreas. "For example, exosomes loaded with miR-122 sensitize HCC cells to sorafenib, and those carrying galectin-9 siRNA enhance immunotherapy in pancreatic ductal adenocarcinoma." (PMID 41361128, 2025). "Serum levels of galectin-9 were proven to differentiate pancreatic ductal adenocarcinoma (PDAC) patients from benign pancreatic disease and healthy subjects." (PMID 39355533, 2024). "Researchers used bone marrow mesenchymal stem-cell-derived exosomes to deliver Galectin 9 siRNA to target pancreatic ductal adenocarcinoma (PDAC) thereby boosting immunotherapy in pancreatic cancer." (PMID 39355533, 2024). "CELC7A (C-type lectin domain family 7, member A) ligates galectin-9 in the tumor microenvironment of pancreatic ductal adenocarcinoma, resulting in the suppression of T cell immunogenicity and reprogramming of tolerogenic macrophages." (PMID 35185876, 2022). "Besides improving T-cell responses, ligand activation of galectin-9 in the tumor microenvironment of pancreatic ductal adenocarcinoma results in tolerogenic macrophage programming and adaptive immune suppression." (PMID 40775219, 2025). "Furthermore, USP10 desensitizes pancreatic ductal adenocarcinoma (PDAC) cells to NK cell-mediated cytotoxicity by deubiquitinating yes-associated protein 1 (YAP1, a core component of Hippo signaling) to transcriptionally upregulate both PD-L1 and galectin-9 (Gal-9)." (PMID 38715050, 2024). "In pancreatic ductal adenocarcinoma (PDAC), LGALS9 polarized macrophages toward a M2 phenotype, leading to the inhibited secretion of T cell cytokines." (PMID 35372038, 2022). "Similarly, the interaction of Dectin-1 with Galectin-9 (Gal-9) and annexin molecules in TME results in detrimental outcomes in a pancreatic ductal adenocarcinoma (PDA) mouse model." (PMID 38668817, 2024).
Allergy (13 papers, 2010 to 2022). An allergy is an immune response or reaction to substances that are usually not harmful. "When combined with its ligands, galectin-9 is implicated in the occurrence and development of various autoimmune diseases, transplant rejection, allergic diseases, infections, and tumors." (PMID 35677161, 2022). "Experiments with dietary interventions including scGOS/lcFOS enhanced local and/or systemic galectin-9 levels in murine and human allergy in association with symptom reduction." (PMID 32457747, 2020). "In a murine food allergy model, NDO were found to enhance galectin-9 expression in IEC, while increasing the serum levels in association with modulation of the mucosal immune response and allergy protection." (PMID 36685520, 2022). "In the current study, OIT + FOS increased serum galectin-9 levels, suggesting direct modulation of IECs and a potential role in allergy protection by OIT + FOS." (PMID 29033945, 2017). "Primarily, galectin-9 is increased in patients with various infectious diseases and allergies." (PMID 35677161, 2022). "Moreover, it was demonstrated that galectin-9 secretion in blood plasma was contributed to exert anti-allergy activity in PCA reaction." (PMID 32050429, 2020). "The up-regulated galectin 9 might suppress allergies, suppress activation, restore phagocytic capacity, and normalize CD103 expression in intestinal DCs." (PMID 30246797, 2018).
malaria (13 papers, 2016 to 2024). Malaria is a serious and sometimes fatal disease caused by a parasite that commonly infects a certain type of mosquito which feeds on humans. "This multifaceted engagement positions certain galectins as possible biomarkers of disease severity, as exemplified by the potential utilization of galectin-9 as a biomarker for severe malaria." (PMID 38067100, 2023). "The overrepresented transcripts in Charles River mice include Galectin-9 (LGALS9), which is an important immune signaling molecule, and Basigin (bsg), a cell surface receptor whose expression is required for infection of RBCs by the human malaria parasite P. falciparum." (PMID 27729904, 2016).
myeloma (13 papers, 2015 to 2025). "Regarding MM specifically, studies have demonstrated the potential of protease-resistant recombinant Galectin-9 (hGal9) to inhibit the proliferation of several myeloma cell lines in vitro, including those resistant to bortezomib." (PMID 39769262, 2024). "Myeloma cells undergo galectin-9-induced intrinsic apoptosis through JNK and p38 MAP kinase pathways." (PMID 28045432, 2017). "The interaction between galectin-9 and its receptor on myeloma cells likely depends on the carbohydrate-recognition function of this lectin because lactose antagonizes its apoptotic effect." (PMID 28045432, 2017). "On the contrary, the frequency of TIM3+ CD8+ T cells showed a significant decrease after knocking down YBX1 in myeloma cells, which was consistent with the decreased expression of LGALS9 in RPMI-8226 with YBX1 knockdown, whereas other exhausted markers remained unchanged." (PMID 36717896, 2023). "In this context, daratumumab may also restore the osteoclast-induced immunosuppressive T-cell phenotype in the myeloma bone marrow milieu by reducing the levels of galectin-9 and a proliferation-induced ligand (APRIL) secreted by osteoclasts." (PMID 35681747, 2022). "For hematologic malignancies, galectin-9 induces the apoptosis of chronic myelogenous leukemia (CML) cells and myeloma cells." (PMID 28045432, 2017). "Counter-receptors for galectin-9 on the CML or myeloma cell surface have not been clarified yet." (PMID 28045432, 2017). "PD-L1 is highly expressed on 5T33 myeloma cells, but the ligands for TIM-3 (galectin-9), LAG-3 (MHC class II), and CTLA4 (CD80) are not." (PMID 25614821, 2015). "In vitro irradiation with 500 cGy did not change the galectin-9, MHC class II or CD80 expression on 5T33 myeloma cells." (PMID 25614821, 2015).